HTT (huntingtin)
Diseases named in the same sentence as HTT in open-access papers (continued):
Sharing a sentence is not in itself a finding about the gene and the disease.
Huntington disease (continued). "Huntington's disease (HD) is a rare genetic neurodegenerative disorder caused by the amplification of CAG repeats in the Huntington (HTT) gene and the accumulation of mutant proteins (mHTT)." (PMID 35547626, 2022). "Huntington’s disease typically appears due to one defective copy of HTT gene for huntingtin that causes progressive degeneration of neurons in the brain." (PMID 36140794, 2022). "Huntington’s disease is an autosomal dominant heritable disorder caused by an expanded CAG trinucleotide repeat at the N-terminus of the Huntingtin (HTT) gene." (PMID 36574405, 2022). "Huntington’s disease (HD) is an autosomal dominant neurodegenerative disorder caused by an expanded polyglutamine (CAG) repeat in exon 1 of the huntingtin (HTT) gene." (PMID 34651228, 2022). "Huntington's disease is a neurodegenerative disorder caused by CAG expansions in the huntingtin (HTT) gene." (PMID 34936701, 2022). "PolyQ containing the huntingtin protein is susceptible to aggregation and has been implicated in Huntington’s disease." (PMID 35438635, 2022). "Huntington’s disease is a single-gene autosomal dominant neurodegenerative disorder with the disease-causing gene IT-15 (the HTT gene)." (PMID 35860666, 2022). "Huntington’s Disease (HD) is caused by the expansion of the polyglutamine (polyQ) tract of the huntingtin protein (HTT)." (PMID 34689261, 2022). "In Huntington’s disease, which is caused by mutations in the HTT gene and abnormal accumulation of the HTT protein, the HTT protein itself induces ELAVL1 to stabilize HTT mRNA, forming a positive feedback loop." (PMID 35465324, 2022). "Huntington’s disease (HD) is a neurodegenerative disease caused by the expansion of the cytosine-adenine-guanine (CAG) repeat in the huntingtin gene." (PMID 36421875, 2022). "Huntington’s disease is an autosomal dominant neurodegenerative disease caused by a CAG expansion within the huntingtin gene (HTT) that leads to the development of a movement disorder, psychiatric and cognitive symptoms." (PMID 35265969, 2022). "Li and colleagues identified molecules which interact with both huntingtin (mHTT) (the causative agent of Huntington’s disease) and autophagosome protein microtubule-associated protein 1A/1B light chain 3 (LC3)." (PMID 35975807, 2022). "The CAG repeat expansion mutation in exon 1 of the huntingtin gene (HTT) causes Huntington disease (HD), a progressive movement disorder with dementia and behavioral abnormalities." (PMID 36071529, 2022). "Huntington’s disease (HD) is caused by a CAG trinucleotide repeat expansion within the coding region of the HTT gene, resulting in an extended polyglutamine (polyQ) tract within the Huntingtin protein." (PMID 36408113, 2022). "Huntington’s Disease (HD) is a fatal neurodegenerative disorder caused by the expansion of a polyglutamine-coding CAG repeat in the Huntingtin gene." (PMID 36499499, 2022). "Huntington's disease (HD) is a progressive neurological disorder that is caused by polyglutamine expansion of the huntingtin (HTT) protein." (PMID 35932982, 2022). "Huntington’s disease is a neurodegenerative disease caused by an expanded polyQ stretch within Huntingtin (HTT) that renders the protein aggregation-prone, ultimately resulting in the formation of amyloid fibrils." (PMID 35948542, 2022). "Mutations in the huntingtin gene can lead to the development of Huntington’s disease, and changes in PSEN1 expression can also cause neurodegeneration and dementia in familial Alzheimer’s disease." (PMID 35805130, 2022). "Huntington’s disease (HD) is an autosomal dominant ND resulting from the mutation in the huntingtin (HTT) gene that presents symptoms, such as cognitive, motor, and psychiatric signs." (PMID 35269720, 2022). "In fact, ATXN3 has been shown to work with HTT, the mutated protein in Huntington’s disease, in a transcription-coupled repair (TCR) complex to repair DNA strand breaks." (PMID 36010688, 2022).
Huntington disease (continued). "Huntington’s disease (HD) is an autosomal, dominantly inherited disorder caused by the expansion of a polyglutamine repeat in the N-terminus of the huntingtin (htt) protein." (PMID 35795689, 2022). "In previous studies, the expansion of polyglutamine (polyQ) bundles to 36 or more glutamine repeats will cause the HTT protein to misfold and aggregate, leading to neuronal death and symptoms of Huntington’s disease." (PMID 35668943, 2022). "Huntington’s Disease (HD) is an autosomal dominant disease caused by a mutation in the gene encoding the huntingtin protein (HTT)." (PMID 36289861, 2022). "Huntington’s disease is caused by a tandem-repeat expansion in the huntingtin gene, which is widely expressed throughout the brain and body, including the gastrointestinal system." (PMID 36035436, 2022). "Huntington’s disease (HD) is an inherited neurodegenerative disease caused by expansion of cytosine–adenine–guanine (CAG) repeats in the huntingtin gene, which leads to neuronal loss and decline in cognitive and motor function." (PMID 35773691, 2022). "Huntington’s disease (HD) is a neurodegenerative disorder caused by the expansion of the CAG repeat in the huntingtin (HTT) gene." (PMID 35219323, 2022). "Huntington’s disease (HD) is caused by the production of mutant Huntingtin (mHTT), characterized by long polyglutamine repeats with toxic effects." (PMID 36499641, 2022). "Huntington’s disease (HD) is a severe inherited neurological disorder caused by a CAG repeat expansion in the huntingtin gene (HTT), leading to the accumulation of mutant huntingtin with polyglutamine repeats." (PMID 35046408, 2022). "Huntington’s disease (HD) is a neurodegenerative disorder caused by a trinucleotide expansion in the HTT gene, which is expressed throughout the brain and body, including the gut epithelium and enteric nervous system." (PMID 35262396, 2022). "Huntington’s disease (HD) is an autosomal dominant neurodegenerative disorder caused by the mutation in the huntingtin (Htt) gene which generates a mutant protein (HTT) with an expanded polyglutamine (polyQ)." (PMID 36611963, 2022). "Huntington’s disease (HD) has an autosomal dominant inheritance caused by an expanded CAG trinucleotide repeat in the HTT gene on chromosome 4, encoding for the protein huntingtin." (PMID 35889562, 2022). "Huntington’s disease (HD) is a dramatic neurodegenerative disorder caused by the abnormal expansion of a CAG triplet in the huntingtin gene, producing an abnormal protein." (PMID 35630602, 2022). "Huntington’s disease (HD) is a neurodegenerative disorder caused by dominantly inherited glutamine repeats (polyQ) in the huntingtin gene (HTT)." (PMID 35821838, 2022). "Huntington’s disease (HD) is an inherited neurodegenerative disease caused by CAG trinucleotide repeat expansion in the first exon of the HTT gene, which encodes the huntingtin protein." (PMID 36293304, 2022). "Huntington’s Disease (HD) is a progressive neurodegenerative disorder caused by CAG trinucleotide repeat expansions in exon 1 of the huntingtin (HTT) gene." (PMID 35241644, 2022). "Huntington’s disease (HD) is an inherited monogenic autosomal dominant neurodegenerative disorder caused by a toxic gain of function of the huntingtin gene (HTT)." (PMID 39483771, 2022). "The HTT gene’s CAG mutation results in Huntington’s disease (HD), leading to a mutant huntingtin protein with a polyglutamine expansion at the N-terminus (mHTT)." (PMID 36364116, 2022). "Perturbation of huntingtin (HTT)’s physiological function is one postulated pathogenic factor in Huntington’s disease (HD)." (PMID 35853002, 2022). "Huntington’s disease (HD) is a neurodegenerative disease caused by CAG repeat expansion in the Huntingtin gene (HTT), including a complex net of pathogenic mechanisms." (PMID 35563107, 2022). "Huntington’s disease (HD) is a fatal neurodegenerative disorder caused by GAG expansion in exon 1 of the huntingtin (HTT) gene." (PMID 36078156, 2022).
Huntington disease (continued). "Huntington’s disease (HD) is a fatal neurodegenerative disorder caused by a polyglutamine expansion in the huntingtin protein." (PMID 35628260, 2022). "Pathophysiology associated with Huntington’s disease (HD) has been studied extensively in various cell and animal models since the 1993 discovery of the mutant huntingtin (mHtt) with abnormally expanded polyglutamine (polyQ) tracts as the causative factor." (PMID 36251090, 2022). "Huntington’s disease (HD) is caused by the production of a mutant huntingtin (HTT) with an abnormally long poly-glutamine (polyQ) tract, forming aggregates and inclusions in neurons." (PMID 35628660, 2022). "Huntington’s disease (HD) is an autosomal dominant neurodegenerative disorder caused by an expansion of a CAG trinucleotide repeat in exon 1 of the huntingtin (HTT) gene." (PMID 35395060, 2022). "Huntington’s disease (HD) is an autosomal dominant neurodegenerative disorder caused by the expansion of the CAG repeat region of the Huntingtin (HTT) gene." (PMID 36192390, 2022). "Huntington’s disease (HD) is a progressive neurodegenerative disorder caused by CAG-repeat expansion in the coding region of the Huntingtin (HTT) transcript, leading to an elongated polyglutamine (poly-Q) stretch in HTT1." (PMID 36357392, 2022). "Huntington’s disease (HD) is a fatal neurodegenerative disorder caused by a CAG repeat expansion in exon one in the huntingtin (HTT) gene." (PMID 36408416, 2022). "We have developed an inducible Huntington’s disease (HD) mouse model that allows temporal control of whole-body allele-specific mutant huntingtin (mHtt) expression." (PMID 36278490, 2022). "Mutant huntingtin (Htt) fragments implicated in Huntington’s disease (HD) generate pathogenic protein aggregates." (PMID 36419510, 2022). "Huntington disease (HD) is a neurodegenerative disease associated with polyglutamine expansion in the protein huntingtin (HTT)." (PMID 36052548, 2022). "Huntington’s disease (HD) is caused by CAG trinucleotide repeat expansion in the HTT gene resulting in a polyglutamine-expanded (polyQ-expanded) mutant huntingtin (mHTT) protein at the N-terminus." (PMID 35943803, 2022). "For instance, protein aggregates due to expansions of poly-Q repeats within exon 1of the huntingtin (HTT) gene cause the Huntington’s disease (HD), which is an incurable neurodegenerative disease characterized by abnormal motility and early death." (PMID 35933423, 2022). "For example, in Huntington’s disease (HD), the mutant huntingtin has been implicated in CNS ER stress and consequent cellular toxicity." (PMID 35888752, 2022). "Huntington’s disease (HD) is a debilitating hereditary motor disorder caused by an expansion of the CAG triplet repeat in the Huntingtin gene." (PMID 36225731, 2022). "Huntington's disease (HD) is a neurodegenerative disease caused by genetic mutation of huntingtin (htt)." (PMID 35670111, 2022). "Abnormal polyglutamine expansion in huntingtin (HTT) protein causes neurodegenerative Huntington’s disease (HD)." (PMID 35853002, 2022). "On the other hand, Huntington's disease (HD) is an autosomal–dominant inherited neurological disorder caused by an unstable trinucleotide CAG repeat expansion at the N-terminus of the IT-15 gene, encoding the ~350 kDa huntingtin protein (Htt)." (PMID 36699535, 2022). "Huntington’s disease (HD) is a progressive autosomal dominant neurodegenerative disorder that is caused by the expansion of a CAG repeat within the huntingtin (HTT) gene that encodes an expanded polyglutamine (polyQ) tract in the HTT protein." (PMID 36278490, 2022). "Huntington disease (HD) is a dominantly inherited neurodegenerative disorder caused by an expansion of a CAG repeat in the HTT gene which leads to a gradual loss of neurons most prominently in the striatum and, to a lesser extent, in cortical brain regions." (PMID 35095420, 2021).
Huntington disease (continued). "Huntington’s disease (HD) is a neurodegenerative disorder caused by the aggregation of the mutant huntingtin (mHTT) protein in nerve cells." (PMID 34869596, 2021). "Huntington’s disease is a genetically inherited neurodegenerative disorder and is caused by a glutamine expansion within the first exon of Huntingtin protein, Htt." (PMID 34831058, 2021). "The HTT is the Huntingtin gene involved in Huntington’s disease, a neurodegenerative disorder characterized by loss of striatal neurons." (PMID 34239411, 2021). "At present, ATTEC technology is mainly used to treat Huntington's disease (HD), a neurodegenerative disease caused by mutated huntingtin (mHTT) and extended polyglutamine (polyQ) stretches." (PMID 34488823, 2021). "Huntington’s disease (HD) is a debilitating neurodegenerative disease caused by mutant huntingtin with an expanded polyQ region containing more than 35 consecutive Gln residues." (PMID 34257293, 2021). "For instance, huntingtin (HTT), an interactor of dynein and kinesin, mutations of which cause Huntington’s disease, was co-transported with beta actin mRNA in a microtubule-dependent manner in rat cortical neurons." (PMID 33341920, 2021). "Huntington’s disease (HD) is an autosomal dominant neurodegenerative disorder caused by an expanded polyglutamine repeat in the huntingtin gene." (PMID 33767215, 2021). "Huntington’s disease (HD) is a neurodegenerative disorder caused by a dominant CAG-repeat expansion in the huntingtin gene." (PMID 33989290, 2021). "Huntington disease (HD) is a fatal autosomal dominant disorder caused by an expanded CAG repeat in the huntingtin (HTT) gene." (PMID 34448021, 2021). "We demonstrate use of DisCo to disrupt condensates of FUS, associated with amyotrophic lateral sclerosis, and to prevent formation of polyglutamine-containing huntingtin condensates, associated with Huntington’s disease." (PMID 33753744, 2021). "PA28γ has been shown to enhance cell survival in an in vitro model of Huntington’s disease (HD), a neurodegenerative syndrome caused by a mutation that leads to an abnormally long polyglutamine (polyQ) expansion in the huntingtin (Htt) protein." (PMID 33562807, 2021). "The causative mutation for Huntington disease (HD), an expanded trinucleotide repeat sequence in the first exon of the huntingtin gene (HTT) is naturally polymorphic and inevitably associated with disease symptoms above 39 CAG repeats." (PMID 38835439, 2021). "Conjugation of siRNA with phosphocholine-docosahexanoic acid (PC-DHA) was used to silence mRNA of Huntingtin (htt), the protein whose mutation results in Huntington’s disease." (PMID 34834395, 2021). "The Huntingtin gene is mostly known to cause Huntington’s disease, being even referenced in a patent to be used as a new therapeutic target to treat this disease, by the expansion of the trinucleotide CAG in its first exon." (PMID 34316711, 2021). "Huntington’s disease (HD) is an autosomal-dominant brain disorder caused by mutant huntingtin (mHtt)." (PMID 34445125, 2021). "Trinucleotide repeat expansions of the huntingtin gene cause Huntington’s disease, a devastating progressive neurodegenerative disorder that manifests in midlife." (PMID 35069097, 2021). "Huntington’s disease (HD) is a dominant neurodegenerative disease caused by an expanded CAG repeat in the HTT gene encoding the Huntingtin protein (HTT)." (PMID 33994545, 2021). "Huntington’s disease (HD) is a dominantly inherited neurodegenerative disorder caused by an expansion in CAG repeats in the exon I of the Huntingtin gene (HTT)." (PMID 34721539, 2021). "Huntington disease (HD) is an autosomal dominant disorder caused by the expansion of a CAG repeat stretch located at the N-terminus of the protein huntingtin (HTT)." (PMID 34445621, 2021).
Huntington disease (continued). "Additional findings from this study implicated mutant huntingtin protein expression in the organ of Corti and reduced expression of brain creatine kinase in the cochlea of this mouse model of Huntington’s disease." (PMID 34539328, 2021). "This complex is implicated in the Huntington’s Disease since triggers the selective degradation of mutated huntingtin through a lysosomal degradation process called BAG3-mediated selective macroautophagy." (PMID 34198675, 2021). "Huntington disease (HD) is a neurodegenerative disorder caused by the expansion of a polyglutamine tract in the huntingtin (mHtt) protein." (PMID 33674575, 2021). "Huntington’s disease (HD) is a progressive brain disorder caused by a dominant mutation in the Huntington (HTT) gene." (PMID 34298977, 2021). "Huntington’s disease is a devastating monogenic neurological disorder caused by the dominantly inherited CAG trinucleotide repeat expansion in the gene encoding the huntingtin (Htt) protein." (PMID 34867159, 2021). "Huntington’s disease is a type of neurodegenerative disease caused by the aggregation of huntingtin proteins containing multiple polyQ sequence repeats." (PMID 34126963, 2021). "Using Huntingtin (HTT) gene causative of Huntington's disease as an example, iE-VP at position 6 significantly enhanced the single mismatch discrimination ability of the RISC without negative impact on silencing of targeting wild type htt gene." (PMID 34850120, 2021). "The CAG expansion of HTT gene results in mutant HTT (mHTT) protein, which causes Huntington’s disease (HD), a debilitative autosomal-dominant brain disorder with worldwide distribution." (PMID 33674575, 2021). "Huntingtin has been at the center of attention as the long-sought gene bearing Huntington’s disease (HD)-causing mutations." (PMID 34803658, 2021). "Huntington’s Disease (HD) is an inherited disorder caused by a CAG trinucleotide repeat expansion (an expanded polyglutamine tract) in the huntingtin gene (Htt)." (PMID 35126052, 2021). "The role of huntingtin, the protein encoded by the HTT gene, has been investigated in models of Huntington’s disease." (PMID 34638589, 2021). "Mutant huntingtin, the disease-causing entity in Huntington’s disease, has an expanded polyglutamine track at the N terminus that causes the protein to misfold and form toxic intracellular aggregates." (PMID 35069097, 2021). "Huntington’s disease (HD) is an incurable neurodegenerative disorder that is caused by polyglutamine expansion in the huntingtin (HTT) protein, characterized by the loss of γ-aminobutyric acid (GABA)-ergic medium spiny neurons (MSNs) in the striatum." (PMID 33869222, 2021). "Huntington’s disease is caused by the misfolding and aggregation of a form of huntingtin protein with an expanded polyglutamine tract at its N-terminal region." (PMID 33981707, 2021). "We have shown previously that monocytes from Huntington’s disease patients are hyper-reactive to stimulation in a manner dependent on their autonomous expression of the disease-causing mutant HTT protein." (PMID 33874957, 2021). "Huntington’s disease is a monogenic autosomal dominant disease caused by polyglutamine tract expansions in the huntingtin protein, while amyotrophic lateral sclerosis (ALS) can be either monogenic or complex." (PMID 33483607, 2021). "Huntington's disease (HD) is a severe autosomal-dominant neurodegenerative disorder caused by a mutation within a gene, encoding huntingtin protein." (PMID 33604336, 2021). "Huntington’s disease (HD) is an inherited autosomal dominant neurodegenerative disorder caused by an elongation of the CAG repeat region of the gene encoding the huntingtin (Htt) protein." (PMID 34955753, 2021). "Huntington’s disease is caused by a mutation in the gene (HTT) encoding the protein huntingtin (Htt) on chromosome 4." (PMID 35095429, 2021).